SLC29A3 (solute carrier family 29 member 3)
Diseases named in the same sentence as SLC29A3 in open-access papers (continued):
Sharing a sentence is not in itself a finding about the gene and the disease.
insulin-dependent diabetes mellitus (8 papers, 2010 to 2025). "Using a MODY panel and NGS, we discovered co-segregation of 2 paternally-inherited mutations of GCK and SLC29A3 with diabetes and 1 paternally-inherited mutation of Apo-A1 with low HDL-C amongst the children." (PMID 34630320, 2021). "A pathogenic homozygous frameshift mutation in the SLC29A3 (c.122del; p.Pro41fs) was identified in another child with isolated diabetes." (PMID 31276222, 2019). "This case demonstrated that SLC29A3 spectrum disorder should be included in the differential diagnosis of diabetes with atypical comorbidities, even when the distinctive dermatological hallmarks of SLC29A3 spectrum disorder are entirely absent." (PMID 35284993, 2022). "We identified six children with monogenic diabetes, including four novel mutations: homozygous mutations in WFS1 (n=3), SLC19A2 and SLC29A3, and a heterozygous mutation in GCK." (PMID 31276222, 2019). "While SLC29A3 disease spectrum is presented as a form of genodermatosis in the literature, even when such classical dermatological hallmarks characterizing the spectrum are not evident, it should be included in the differential diagnosis of atypical courses of diabetes." (PMID 35284993, 2022). "The spectrum of causative genes (PTF1A, GLIS3, WFS1, INSR, SLC29A3, ZNF808, ABCC8, INS) is markedly different from the monogenic diabetes genes seen in non-consanguineous cohorts, and also different from those seen in other consanguineous populations." (PMID 37897565, 2023). "The two maternal aunts (I-3, I-4) with diabetes and deafness did not carry the GCK or SLC29A3 mutations or mtA3243G mutation." (PMID 34630320, 2021).
hypertrichosis (6 papers, 2010 to 2025). Excessive hair growth anywhere on the body. "Defects in the SLC29A3 gene cause hyperpigmentation or hypertrichosis." (PMID 35284993, 2022).
Lymphadenopathy (5 papers, 2010 to 2026). Enlargement (swelling) of a lymph node. "Although the lymphadenopathy in Rosai-Dorfman disease is considered a reactive rather than a neoplastic process, the occurrence of two early onset cancers in the proband of Family 1 raised the possibility that SLC29A3 inactivation might cause cancer susceptibility." (PMID 20140240, 2010).
sinus histiocytosis with massive lymphadenopathy (5 papers, 2010 to 2025). A rare disorder of unknown etiology characterized by distention of the lymph node sinuses and sinusoidal histiocytic infiltration. "Hence the analysis of the SLC29A3 pathway in sporadic Rosai-Dorfman disease, will be of interest." (PMID 20140240, 2010).
anemia (4 papers, 2019 to 2023). A reduction in the number of red blood cells, the amount of hemoglobin, and/or the volume of packed red blood cells. "Mutations in ENT3, encoded by SLC29A3, result in anaemia and erythroid hypoplasia, suggesting roles in erythropoiesis." (PMID 33623001, 2021). "Interestingly, an increasing number of human genetic disorders are being attributed to mutations in the human SLC29A3 gene (encodes ENT3) with anemia, bone marrow failure, and hepatosplenomegaly as common accompanying features." (PMID 35804885, 2022). "Mutations in human equilibrative nucleoside transporter 3 (ENT3) encoded by SLC29A3 results in anemia and erythroid hypoplasia, suggesting that ENT3 may regulate erythropoiesis." (PMID 33623001, 2021). "Mice deficient for the mouse orthologue of human ENT3 (mENT3) develop severe anemia and early mortalities, and through screening a mouse knockout library of 472 transmembrane proteins, it was discovered that Slc29a3 (which encodes mENT3) is a critical gene in the development of RBCs13,14." (PMID 33623001, 2021). "However, the relationship between erythropoiesis and ENT3 and the molecular pathogenesis of anemia in SLC29A3 mutation-driven disorders remains poorly understood." (PMID 33623001, 2021). "The mouse phenotypes recapitulate the disease symptoms observed in human ENT3 disorders, including anemia, suggesting that Slc29a3-deleted mice are a suitable model for further evaluating ENT3 hematopoietic disease pathologies." (PMID 35804885, 2022). "As a result, cytoprotective UPR signaling mediated through the IRE1α signaling branch is likely resisting anemia in young Slc29a3−/− mice until 8 weeks of age." (PMID 33623001, 2021). "Nevertheless, the identification of bona fide erythroid-to-myeloid skewing provided a compelling explanation for the exacerbated formation of histiocytes and leukocytes with accompanied anemia and thrombocytopenia in Slc29a3−/− mice." (PMID 31270333, 2019). "Indeed, HSCs in Slc29a3 KO mice display high levels of basal ER stress with reduced accumulation of taurocholic acid (a chemical chaperone), suggesting that a lack of utilization of BA contributes to increased ER stress-induced anemia in SLC29A3 disorders." (PMID 35804885, 2022). "Thus, the long-term decrease in HSPCs and defective erythroid line of differentiation may underlie the impairment in blood cell regeneration and contribute to anemia in Slc29a3−/− mice." (PMID 33623001, 2021). "Moreover, HSC transplantation in Slc29a3-null mice increased survivability with notable improvement in health, whereas treatment with synthetic adenosine analogs (e.g., AICAR) resulted in only a partial recovery of ENT3 dysfunctions, including anemia, in Slc29a3 KO mice." (PMID 35804885, 2022).
lung carcinoma (3 papers, 2010 to 2024). "The MAF of the SNPs, DCK -360C>G (80143932), SLC29A1 -201A>G (760370), SLC29A1 +913C>T (9394992), SLC29A3 +4967C>A (10999776) in lung cancer patients was 2%, 15%, 23.2%, and 24.4% respectively." (PMID 39564037, 2024). "SLC29A3, encoding ENT3, affects overall survival (OS) and response to gemcitabine-based chemotherapy in lung cancer patients." (PMID 38534987, 2024).
Langerhans cell histiocytosis (2 papers, 2010 to 2012). Langerhans cell histiocytosis (LCH) is a systemic disease associated with the proliferation and accumulation (usually in granulomas) of Langerhans cells in various tissues. "RF has never before been reported in a patient with SLC29A3 mutation, but was frequently associated with Erdheim-Chester disease, another rare non-Langerhans cell histiocytosis of unknown origin." (PMID 22238637, 2012). "It is unclear if SLC29A3 might prove to be relevant to the pathogenesis of other non-familial histiocytic disorders but we note that the use of nucleoside analogues for the therapy of Langerhans cell histiocytosis has been suggested previously." (PMID 20140240, 2010).
leprosy (2 papers, 2022 to 2024). Leprosy is a chronic infectious disease affecting primarily the skin and peripheral nervous system. "Furthermore, the research group has identified SLC29A3 as a susceptibility gene for leprosy, which encodes equilibrative nucleoside transporter 3 (ENT3)." (PMID 38440733, 2024). "We were able to replicate leprosy associations at 2 loci; a missense SNP in LACC1, rs3764147 (p = 0.004, OR = 1.36 95% CI 1.10 − 1.67), and a missense SNP in SLC29A3, rs780668 (p = 0.034, OR = 1.28 95% CI 1.02 − 1.60)." (PMID 36121873, 2022). "In doing so we replicate known leprosy susceptibility loci at MHC class I and II, LACC1 and SLC29A3." (PMID 36121873, 2022). "Furthermore, we replicate previously identified leprosy susceptibility loci at LACC1, SLC29A3, and with HLA Class I and II alleles." (PMID 36121873, 2022).
Autoimmunity (1 paper, 2025). The occurrence of an immune reaction against the organism's own cells or tissues. "Recent studies have stated that SLC29A3 mutations are related to autoinflammation and autoimmunity due to the activation of inflammatory processes by mitochondrial and lysosomal dysfunction." (PMID 39992598, 2025). "This current study shows the genetic changes in genes related to autoimmunity such as pathogenic variants of IL36RN, RNASEH2B, and SLC29A3 genes." (PMID 39992598, 2025).
bladder cancers (1 paper, 2010). "Initially we screened for SLC29A3 mutations in a panel of 6 breast cancer cell lines (MCF7, HCC1143, HCC1395, HCC1937, HCC1806 and HCC1419) and 37 bladder cancer cell lines." (PMID 20140240, 2010).
cystic teratomas of the ovary (1 paper, 2022). "Among the 15 prevalent mutated genes, 8 with different variants in exons with changes in protein coding are important for the development of mature cystic teratomas of the ovary: FLG, MUC17, MUC5B, RP1L1, NBPF1, SLC29A3, SGK223, and FAM186A." (PMID 36289533, 2022).
depressive disorder (1 paper, 2020). A melancholy feeling of sadness and despair. "The results suggested that abnormalities in adenosine transport due to variation among women of the nucleoside transporter gene SLC29A3, could predispose to depression, with genetics of mood regulation possibly varying between the sexes." (PMID 32178222, 2020). "Selecting 117 single nucleotide polymorphisms from 13 genes, a negative association between SLC29A3 polymorphism rs12256138 and depressive disorders was found among women." (PMID 32178222, 2020).
hyperferritinemia (1 paper, 2025). "SLC29A3 homozygous variant was reported in cases with systemic juvenile idiopathic arthritis and hyperferritinemia." (PMID 39992598, 2025).
Hypocholesterolemia (1 paper, 2019). An decreased concentration of cholesterol in the blood. "Consistently, Slc29a3−/− mouse plasma displayed severe dyslipidemic features, including hypocholesterolemia, hypotriglyceridemia, and hypolipoproteinemia." (PMID 31270333, 2019).
immune deficiencies (1 paper, 2022). "Different forms of immune deficiencies related to SLC29A3 disease spectrum have also been presented in the literature." (PMID 35284993, 2022).
leukaemia (1 paper, 2010). "In view of two early onset cancers in a proband with FHC we wondered whether SLC29A3 might predispose to neoplasia (e.g. by altering adenosine metabolism as extracellular adenosine has been reported to induce apoptosis and proliferation in gastric, leukaemia and hepatic cancer cell lines)." (PMID 20140240, 2010).
osteosclerosis (1 paper, 2022). Abnormally high bone density. "He had unique metadiaphyseal splaying and osteosclerosis, vertebral end‐plate osteosclerosis, and cortical thinning of long bones but no mutation was detected of SLC29A3, TNFRSF11A, TCIRG1, LRRK1, or CSF1R associated with DSS." (PMID 35991533, 2022).
genetic disorders (6 papers, 2018 to 2025). "Consistently, ENT3 is widely expressed in many tissues including bone marrow, liver, placenta, pancreas, skin, heart, GIT, brain, fat, and skeletal muscle, mirroring the pattern of dysfunction observed in SLC29A3-mutated genetic disorders." (PMID 35804885, 2022). "Mutations in equilibrative nucleoside transporter 3 (ENT3), encoded by SLC29A3, cause a spectrum of human genetic disorders." (PMID 31270333, 2019).
neoplasia (3 papers, 2010 to 2023). "Further clinical studies are required to determine whether the frequency of neoplasia in SLC29A3 spectrum disorder is increased or whether the findings in the FHC family are coincidental." (PMID 20140240, 2010).
SLC29A3 also shares sentences with these, for which no sentence is quoted: hypogonadism (4 papers); osteopetrosis (4); cancer (3); dysosteosclerosis (3); deafness (2); dermatosis (2); Hyperglycemia (2); infection (2); lysosomal disorders (2); Platyspondyly (2); Splenomegaly (2); acute leukemia (1); Aicardi-Goutières syndrome (1); aplastic anemia (1); atrial fibrillation and flutter (1); atrial septal defect (1); autosomal recessive disease (1); bladder tumours (1); Blau syndrome (1); bone marrow failure (1); breast carcinoma (1); Camptodactyly (1); colitis (1); colorectal cancer (1); developmental delay (1); Erdheim-Chester disease (1); familial cold autoinflammatory syndrome (1); familial Mediterranean fever (1); Fever (1); genodermatosis (1).
A further 19 diseases each share a sentence with SLC29A3 in 1 paper.